LEP (leptin)
Diseases named in the same sentence as LEP in open-access papers (continued):
Sharing a sentence is not in itself a finding about the gene and the disease.
Obesity (continued). "However, the leptin resistance in children does not correlate with in utero exposure to maternal overweight/obesity or gestational diabetes mellitus." (PMID 38542187, 2024). "The aim of this study was to determine whether or not interventions combining IF plus Exe are more effective than Exe only for improving serum leptin and adiponectin in adults with and without obesity." (PMID 38933888, 2024). "In addition, leptin and insulin function synergistically on various POMC neuronal subpopulations to enhance WAT browning and energy expenditure, as well as to protect against diet-induced obesity." (PMID 39590824, 2024). "However, leptin-based therapeutics in clinical trials have failed to effectively treat obesity, predominately owing to leptin resistance in most people with obesity." (PMID 38310105, 2024). "Mice lacking leptin or its receptor exhibit severe obesity due to overeating." (PMID 39457523, 2024). "However, chronic overexpression of leptin can lead to leptin resistance, a condition where the body no longer responds effectively to the hormone’s signals, often observed in obesity." (PMID 39570663, 2024). "The expansion of adipose tissue leads to increased levels of leptin in the bloodstream as well as the oxidation of low-density lipoprotein (LDL) cholesterol and an increase in the secretion of inflammatory cytokines, thereby triggering oxidative stress in obesity." (PMID 38732125, 2024). "Previous studies have illustrated the anti-obesity effects of mixtures of Lactobacillus curvatus HY7601 and Lactobacillus plantarum KY1032, mediated through the regulation of adipogenic factors, such as adiponectin and leptin, by means of both animal experiments and clinical trials." (PMID 39125449, 2024). "Notably, individuals with the CLOCK (CC), FTO (AA), and LEP (AA) genotypes exhibited the highest BMI and WHR, while those with GHRL (TT), MC4R (CC), and LEPR (GG) genotypes, although showing lower values, were still correlated with overweight and obesity." (PMID 39203789, 2024). "However, to our knowledge, a specific role for increased leptin levels in facilitating or mediating brain inflammation during obesity has not been established." (PMID 36769012, 2023). "Our hypothesis also suggests that obesity will not occur in everyone as it requires an interaction in which one becomes leptin resistant (from fructose metabolism) and then ingests high energy foods (such as fat)." (PMID 37482773, 2023). "The major tissues responsible for obesity are the adipose tissues, which are not mere depots for fat storage, but also act as an active endocrine organ and secrete various adipokines, including adiponectin, leptin, and resistin." (PMID 36729332, 2023). "It appears that obesity could modify inflammatory biomarkers and immune system activity directly or indirectly, in addition, the inflammatory factors, such as hs-CRP and leptin may lead to the altered metabolic indices." (PMID 37208686, 2023). "Although these observations led to substantial interest in the clinical use of leptin for obesity, exogenous leptin treatment is not effective in most obese patients, nearly all of whom already exhibit significantly elevated plasma leptin levels but diminished leptin responsiveness." (PMID 37002197, 2023). "It revealed that leptin sensitivity might revert to normal functioning when adipose tissue was decreased and HIIT-induced aerobic fitness (VO2max) promotion in female teenagers (mean age 14.2 years) affected by obesity." (PMID 37608837, 2023). "The data suggest elevated insulin signaling (hyperinsulinemia) promotes weight gain and an increase in fat mass with a concomitant increase in circulating leptin levels inducing central insulin and leptin resistance, subsequently leading to obesity, hyperphagia and lack of satiety." (PMID 37546289, 2023).
Obesity (continued). "All together, these data could suggest that in leptin resistant states (including simple obesity), there could be lack of both inhibitory effect of leptin on D6D and D9D activity and stimulatory effect of leptin on D5D activity." (PMID 37545582, 2023). "The extended analysis of the subgroups (ASD+/Ob+, ASD+/Ob−, ASD−/Ob+, and ASD−/Ob−), stratified for gender, revealed no statistical significance in median leptin levels between females and males with overweight/obesity either before or after puberty (the ASD+/Ob+ and ASD−/Ob+ groups)." (PMID 36902307, 2023). "The most prominent and ubiquitous characteristic of children identified with biallelic (likely) pathogenic variants in LEP, LEPR, and MC4R genes was the onset of severe obesity and hyperphagia at a very young age—they lacked satiety and were constantly in demand of food." (PMID 37659411, 2023). "VMH may be the origin of leptin-mediated sympathoexcitation which contributes to obesity-related hypertension, but no cardiovascular effects were reported in these mutant mouse models." (PMID 36670468, 2023). "It is likely that Slug may have additional epigenetic targets involved in leptin resistance and obesity, such as positive regulators, like Sh2b1, and negative regulators, like SOCS3 and PTP1b, of LepRb signaling." (PMID 36512408, 2023). "LEP mRNA levels were higher in patients with obesity in both fat depots regardless of sex." (PMID 36833305, 2023). "Mice lacking SHP2 in the brain develop early-onset obesity and leptin resistance." (PMID 38027481, 2023). "Exposure to chronic hypoxia may modulate plasma leptin levels through hypoxia-inducible factor 1, and thus produces negative feedback on appetite to prevent obesity." (PMID 37394907, 2023). "In addition to leptin and adiponectin, ghrelin and glucagon-like peptide 1 (GLP-1), are altered during obesity and also influence bone metabolism, and may have a role in bone remodeling." (PMID 36831188, 2023). "Interestingly, while diet-induced obese mice exhibit elevated heart rate and blood pressure, mice lacking leptin or leptin receptors maintain normal blood pressure despite severe obesity." (PMID 38027481, 2023). "Asthma showed significantly higher leptin level than that in non-asthma controls, which might be due to the effects of leptin in the inflammation, obesity and lung development." (PMID 36914629, 2023). "In addition, obesity promotes tumour growth and T-cell exhaustion with PD-1 upregulation in tumour-infiltrating CD8+ T-cells in both B16F0 melanoma and 4T1 BC murine models, which were shown to be partly mediated via leptin." (PMID 37173907, 2023). "When comparing the concentrations of leptin in the first trimester and at the time of cesarean section, a significant increase was found in pregnant women with normal weight (p = 0.004) and obesity (p = 0.043) but not in others i.e. mothers with overweight body mass index." (PMID 36771307, 2023). "However, the impact of obesity on bone health appears to have both positive (e.g., increased leptin, mechanical loading) and negative (e.g., increased inflammation, fewer mesenchymal stem cells directed to osteoblasts) effects." (PMID 37990680, 2023). "Meanwhile, leptin-induced STAT3 phosphorylation was significantly impaired under Slc7a5 deficiency in LepR-expressing VMH neurons, but not in ARC neurons, prior to the onset of obesity." (PMID 36862514, 2023). "Unlike the results in RBP4 and asprosin, obesity could independently or collectively act as an interfering factor in significantly upregulating the expression of leptin, nampt/visfatin and resistin." (PMID 38069063, 2023). "The following part of the review describes the key roles of adiponectin, leptin, resistin, IL-6, MCP-1 and PAI-1 recognized to be involved in the physiopathology of obesity and cited as relevant targets for limiting metabolic and vascular complications in obesity." (PMID 38136564, 2023).
Obesity (continued). "It is not unexpected that reduced LepRb expression results in leptin resistance and obesity." (PMID 36512408, 2023). "For instance, leptin couples changes in weight to changes in blood pressure so that mice and humans lacking leptin or its receptor have low blood pressures, despite severe obesity, in line with the reduced diastolic blood pressure seen in deletion carriers compared with BMI-matched non-carriers." (PMID 37586323, 2023). "It is important to note that leptin therapy is not FDA-approved for obesity management." (PMID 37937009, 2023). "However, the interactions between spontaneous neural activity and adipokines (leptin and adiponectin) during IER interventions in obesity remain unclear." (PMID 37600013, 2023). "It has been proposed earlier that alternative pathways may be more significant with progressive and persistent obesity as opposed to VD-mediated suppression of leptin secretion from adipocytes." (PMID 37686748, 2023). "Overall, while the relationship between SCFE and leptin is not fully understood, elevated leptin levels may be a risk factor for SCFE even independent of obesity status." (PMID 37108990, 2023). "However, our cross-sectional study showed for the first time that FGF21 and leptin were able to discriminate the metabolic state in children without and with obesity, respectively." (PMID 38138907, 2023). "Importantly, the AL ratio can specifically tell the lean control from the lean or overweight/obesity NAFLD group rather than adiponectin or leptin alone." (PMID 36790383, 2023). "Leptin levels are higher in individuals with obesity compared to those without obesity." (PMID 36983642, 2023). "Notably, PBMC Syn1 expression appears as an accessible biomarker of cognitive health, reflecting both the detrimental effect of HFD intake at early ages despite the absence of obesity and the positive effects of neonatal leptin treatment on cognition." (PMID 38203399, 2023). "Furthermore, this indicates that interactions between the central leptin system and the endogenous opioidergic system may mediate the effects of ELT on binge eating habits and vulnerability to obesity." (PMID 36510113, 2023). "Interestingly, both leptin and another molecule, resistin correlate with other inflammatory markers of obesity, independent of BMI." (PMID 36788619, 2023). "The frequent observation that TSH levels are elevated during obesity is not regarded as a functional defect, but as a mere manifestation of a deranged hypothalamic–pituitary axis or an increase in leptin-induced TRH production and type 2 iodothyronine deiodinase (D2) inhibition in the thyrotrophs." (PMID 37248529, 2023). "Our results showed that in female patients with severe obesity with or without MetS, weight loss induced by bariatric surgery with RYGB improved biochemical and systemic inflammatory parameters, particularly the adiponectin/leptin ratio." (PMID 37571250, 2023). "Although individuals with obesity produce more leptin, they may not experience increased appetite suppression because people with greater adiposity develop leptin resistance." (PMID 37239728, 2023). "This is shown by the dramatic obesity in individuals (mice and humans) lacking leptin." (PMID 37661748, 2023). "Studies based on the interaction between serum proteins and leptin show that human CRP directly inhibits the binding of leptin to the receptor in vitro and blocks the signaling pathway of leptin, which suggests that CRP can promote obesity and metabolic complications." (PMID 37893085, 2023). "We explored the interaction between leptin/obR signaling and M1 macrophage polarization in obesity-related neutrophilic airway inflammation using a lipopolysaccharide (LPS)/ovalbumin (OVA) + OVA-treated obese mouse model, which has features similar to those of obesity-related asthma." (PMID 37488474, 2023).
Obesity (continued). "They found that obesity was significantly related to a nonresponse to the hepatitis B vaccine, potentially due to mechanisms such as leptin-induced systemic and B-cell intrinsic inflammation, impaired T-cell responses, oxidative stress, and chronic low-grade inflammation." (PMID 37064020, 2023). "In addition, while chronic inhibition of AGRP neurons fails to alter food intake and body weight in ob/ob mice, chronic inactivation of all GABAergic neurons in the ARH largely ameliorates hyperphagia, hyperglycemia and obesity in mice lacking leptin." (PMID 38027481, 2023). "However, further analysis of the available data leads to the conclusion that leptin is not thermogenic and that the obesity in the ob/ob mice cannot be understood as being due to brown adipose tissue inactivity." (PMID 37661736, 2023). "Similarly, humans and animals lacking leptin or LepRb are unable to sense adipose energy stores and thus exhibit voracious feeding and decreased energy expenditure despite their severe obesity." (PMID 37581939, 2023). "Genetic obesity models, including leptin-deficient fatty (fa/fa) Zucker rats or (ob/ob) mice, are used to investigate obesity and metabolic dysfunction, yet these genetic models of obesity do not include changes in leptin, and, therefore, cannot completely mimic the diet-induced human disease." (PMID 34976743, 2022). "Furthermore, individuals with obesity have reduced fasting levels of PYY and GLP-1 and blunted meal-stimulated levels of these anorectic peptides, in addition to an attenuated satiety-promoting effect of CCK, leptin resistance, and IR." (PMID 35334929, 2022). "Also, in mice fed a HFD to induce obesity, we found that IMC treatment significantly altered the oscillatory patterns of key host metabolic hormones insulin, leptin, and adiponectin, which is likely to play a modulatory role in downstream lipid metabolic phenotypes." (PMID 35072627, 2022). "However, three weeks of consuming the obesogenic WD was not sufficient to significantly alter critical peripheral obesity biomarkers, including leptin, insulin, triglycerides, and corticosterone (p > 0.05)." (PMID 35220393, 2022). "In women, but not in men, increased serum leptin may contribute to a decline in eGFR that is independent of obesity and diabetes mellitus." (PMID 36555328, 2022). "However, most cases of human obesity are characterized by resistance to leptin action therefore no benefits from hyperleptinemia are observed." (PMID 35945482, 2022). "Moreover, this correlation was observed in the control group, with less obesity parameters and leptin levels, but not in the drug allergic patients." (PMID 36327304, 2022). "Moreover, while lean humans show a post-prandial decrease in plasma AEA and leptin levels, this does not occur in individuals with obesity." (PMID 36111295, 2022). "Hypocaloric diets are known to induce changes in adipokine secretion, but the influence of a low energy liquid diet (LELD) on the leptin: adiponectin ratio (LAR), a measure of insulin resistance and cardiovascular risk, has not previously been investigated in patients with severe obesity." (PMID 35662920, 2022). "In obesity, its mechanisms are not fully elucidated but may involve leptin and activation of the brain melanocortin system." (PMID 36010152, 2022). "Interestingly, leptin levels are high (hyperleptinemia) in humans with common obesity without affecting appetite and body weight regulation, probably indicating a state of leptin resistance in the CNS." (PMID 36556424, 2022). "In the animals with HFD and non-KD-induced obesity, the anorectic effect of leptin was suppressed." (PMID 36432492, 2022). "Furthermore, investigation of the human fasting metabolome in persons without obesity confirm hypoleptinemia occurs in the early phases of fasting and that plasma leptin is inversely correlated with NEFA." (PMID 35629964, 2022).
Obesity (continued). "Therefore, next-generation DNA sequencing of central genes in the leptin-melanocortin pathway was performed in 1508 children and adolescents with and without obesity, aged 2-19 years." (PMID 35574020, 2022). "Therefore, in obesity patients, the protective effect of leptin and the negative impact of fat distribution on central obesity will affect the outcome of the development of CSA." (PMID 35162313, 2022). "Thus, the absence of leptin in individuals with sufficient energy due to inborn error promotes obesity." (PMID 35388304, 2022). "Furthermore, it cannot be excluded that the ratio adiponectin/leptin is possibly more important rather than the individual serum levels of the two adipokines in obesity and obese women." (PMID 35563854, 2022). "Unfortunately, biochemical measurements of inflammatory cytokines, IGF-1, and leptin were not available in our study, and these may help to better clarify the relationship between obesity and bone health." (PMID 35865318, 2022). "Therefore, we are not able to clearly define the effect of breast milk leptin on the prevention of obesity in breastfed children." (PMID 35684517, 2022). "No family history of obesity was observed with these heterozygotes of LEP rs570757178C/G." (PMID 36619235, 2022). "However, obesity is characterized by impaired leptin signaling despite elevated leptin levels, or even leptin resistance resulting in no therapeutic effects of leptin administration in people with obesity." (PMID 35743630, 2022). "Obesity is not always synonymous of EMS, but obesity is clearly a risk factor, and is characterized by significant increase in blood cortisol and a correlation between blood leptin and body condition score." (PMID 36557769, 2022). "Although the extreme ranges for upper (overweight/obesity) and lower BMI values (underweight) are not present in this reference cohort, we assume that these references can be used to detect discrepancies between given BMI value and circulating leptin levels." (PMID 35677722, 2022). "Also, the A/L ratio was shown to be a stronger correlate to IR than adiponectin or leptin alone, an independent predictor of insulin sensitivity (IS) in women with moderate obesity and men presenting obesity without or with MetS, glucose intolerance or T2D." (PMID 35436409, 2022). "This study explored the effect of three different modes of resistance training on appetite hormones [leptin, ghrelin, cholecystokinin (CCK), glucagon-like peptide-1 (GLP-1), and peptide tyrosine–tyrosine (PYY)], cardiometabolic and anthropometric measures in males with obesity." (PMID 35264977, 2022). "Finally, BID does not regulate obesity induced by increased food update as manifested by the effect of leptin, suggesting that its effect toward the composition of the food, high fat, can be overcome by the amount of food." (PMID 36382356, 2022). "It seems that the negative effect of leptin also plays a critical part in obesity." (PMID 35883424, 2022). "However, no hyperphagia or obesity was observed in adult zebrafish lacking lepr, suggesting that the regulatory role of leptin in adipostasis is not conserved in vertebrates." (PMID 35937837, 2022). "In a study that included 13 infants with bronchiolitis, it was shown that the severity of viral bronchiolitis in infancy may be associated with the profile of adipokines, in particular with the leptin/adiponectin ratio, but not with obesity." (PMID 36291711, 2022).